IL33 (interleukin 33)
Diseases named in the same sentence as IL33 in open-access papers (continued):
Sharing a sentence is not in itself a finding about the gene and the disease.
tumor (continued). "Based on these results, it is plausible that IL-33 secreted from stellate cells or CAFs acts on other cells, such as macrophages, that are reported to express ST2L and CXCL3, rather than on tumor cells themselves to stimulate the secretion of CXCL3." (PMID 32340025, 2020). "In orthotopic but not subcutaneous mouse models, IL-33 activates ILC2s, which in turn produce CCL5 to recruit CD103+ cDC1s to the TME which then prime and activate CD8 T cells to infiltrate the tumor and exert an anti-tumor immune response." (PMID 33584701, 2020). "They showed that IL-33 treatment increased the expression of PD-1 on TILC2, but not in draining LN ILC2, indicating selective activation in the tumor immune compartment." (PMID 33329534, 2020). "First, we evaluated IL-33 and ST2 levels in tumor, distant non-tumor tissue and plasma from CRC patients." (PMID 31281317, 2019). "Fittingly, absence of IL-33/ST2 signaling reduced the accumulation, proliferation, and immunosuppressive ability of MDSCs in tumor-bearing mice." (PMID 30483263, 2018). "In our study, IL-33 expanded eosinophils expressed T cell-attracting chemokines and induced NK and CD8+ T cell-recruitment at the subcutaneous tumor site, but not at the lung metastatic site." (PMID 30483263, 2018). "Our study shows that the absence of IL-33 signaling affects the recruitment of CD4+ T cells, dendritic cells, macrophages, and NK cells to the tumor microenvironment." (PMID 30112116, 2018). "Infection of patient-derived NSCLC cells with gram-negative bacteria enhanced tumor proliferation, invasion, and metastasis by activation of TLR4 in NSCLC cells resulting in increased IL-33 expression though a MyD88-dependent pathway." (PMID 30205617, 2018). "IL-33 is upregulated in PDAC and nonmalignant cells in the tumor microenvironment of PDAC and lesions from chronic pancreatitis: pancreatic stellate cells and pancreatic myofibroblasts have been identified as important sources of this cytokine." (PMID 30426271, 2018). "IL-33-treated and non-treated macrophages were mixed with GFP+ LLC tumour cells and spreading of GFP+ cells was quantitatively measured." (PMID 27150562, 2016). "The IL-33/ST2 pathway regulates Th1/Th2 immune responses in autoimmune and inflammatory conditions, but the role of ST2 signaling in tumor growth and metastasis has not been investigated." (PMID 21484786, 2011). "We found that IL-33/ST2 signalling has a direct effect on the motility, invasion and proliferation SCC cells, and it is independent of tumour ‘plasticity’ genes, including neuroendocrine markers and genes that participate in epithelial-to-mesenchymal transition (EMT) and stemness." (PMID 38662248, 2024). "Interestingly, the profound impact of rIL-33 on tumor immunity in the LLC lung cancer model was not replicated in MyD88-/- mice, underscoring the crucial role of the MyD88 pathway in mediating IL-33’s immunomodulatory effects." (PMID 38881897, 2024). "As a result, the expression of IL-33 by the tumor may allow the activation of the ILC2 function, whereas the lack of IL-33 expression would not support these immune cells." (PMID 31130612, 2019). "Similarly, both IL-33 and ST2 were up-regulated in ovarian tumors compared to normal ovary and ovarian benign tumors, and the expression levels were further increased in tumor tissues at the metastatic site." (PMID 30483263, 2018). "Similarly, tumour cells produced negligible levels of IL-33 in PDGF-BB-positive and -negative tumour cells, which remained unchanged." (PMID 27150562, 2016). "Thus, the combination of IL-33 and anti-CSF1R or p38 inhibitor could avoid the negative immune regulation of IL-33-induced M2 polarization, which has synergistic anti-tumor effect." (PMID 38238529, 2024). "However, in the tumor microenvironment, the classical suppression of tumorigenicity 2 (ST2)–IL33 pathway might not be the dominant pathway." (PMID 36726981, 2022).
tumor (continued). "Additionally, the expression of ST2 L was found to be lower in human tumors relative to adjacent non-neoplastic tissue—the higher the tumor grade, the lower the expression of ST2 L. All together, these results support a potential antitumorigenic role of the IL-33/ST2 axis." (PMID 34071419, 2021). "The observation that ICAM-1 did not compensate for lack of CD11b-mediated adhesion in EO-tumor cell conjugates upon CD11b/CD18 blockade further supports the major role played by CD11b/CD18 in mediating tumor cell adhesion and subsequent cytotoxicity in IL-33 EO." (PMID 31717819, 2019). "Compared to the control IgG group, neutralizationof ST2L significantly decreased the tumor size in tumor-bearing mice (P< .05), accompaniedby inhibition of the serum ST2L, but not sST2 and IL-33, suggesting neutralization of ST2Lmay not regulate sST2 and IL-33 expression." (PMID 29950152, 2018). "Indeed, abundant IL-33 proteins were detected in mouse CRC tumours compared with normal tissues (colon, small intestine, liver, spleen and lung) irrespective of sST2 expression levels in the tumour cells." (PMID 27882929, 2016). "Hence, while the expression of PD-1 on tumor ILC-1s has been extensively reported, several questions remain; namely, whether tumor alarmins drive PD-1 expression and whether PD-1 intrinsically inhibits antitumor function of ILCs within the TME in the absence of exogenous IL-33." (PMID 37098069, 2023). "Interestingly, IL-33 could transform non-stem cells to GBM stem cells, activate disintegrin and metalloproteinase with thrombospondin motifs 5 (ADAMTS5) and EGFR by promoting the accumulation of tenascin-C (TNC), which in turn exacerbates GBM tumor cell proliferation." (PMID 35572545, 2022).
infection (403 papers, 2008 to 2026). The state of being infected such as from the introduction of a foreign agent such as serum, vaccine, antigenic substance or organism. "Upon infection with H. polygyrus, the IL-33 alarmin accumulated in the bone marrow, causing EMPPs to upregulate the GATA co-factor LMO4 and preferentially differentiate into myeloid cells." (PMID 41813898, 2026). "IL-33 has been shown to activate a wide range of immune cells associated with type 1 immunity, infections, and chronic inflammation, including Th1 cells, nature killer (NK) cells, CD8+ T cells, neutrophils, macrophages, B cells, and NKT cells." (PMID 39925809, 2025). "This strong statistical correlation, coupled with the known role of IL-33 as an alarmin enhancing the immune response during tissue damage and infection, provides a compelling link between genetic predisposition and heightened inflammatory response in CSU." (PMID 39769469, 2024). "Previous studies have reported that IL-33, acting as an alarmin, is released upon cell death caused by cellular stress, tissue injury, and infections." (PMID 38319737, 2024). "Recent studies reported that IL‐33 caused naive T cellular senescence in mice during severe infection." (PMID 39465143, 2024). "During later stages of infection, these cells respond to IL-25 and IL-33 to promote the activation of pathogenic T helper cells that favor fungal survival and support cryptococcal dissemination to the brain." (PMID 37337050, 2023). "In humans, it was suggested that IL-33/ST2L in VL can be considered a potential prognostic marker for susceptibility to this infection." (PMID 37512804, 2023). "Since IL-33 release is classically associated with cell death we next quantified the number of both astrocytes and oligodendrocytes post-infection." (PMID 37983247, 2023). "Alarmins are epithelial-derived cytokines, such as thymic stromal lymphopoietin (TSLP), interleukin 33 (IL-33), and IL-25, released in response to the cellular damage caused by cellular stress or infection." (PMID 38201921, 2023). "Analysis of RNAseq datasets revealed 251 significantly differentially expressed genes when comparing B6/J and IL-33 deficient macrophages during infection." (PMID 37983247, 2023). "IL-33 is a cytokine of the IL-1 family that is classically associated with infection and inflammatory diseases." (PMID 36869026, 2023). "While ~75% of wild type animals survived infection, both Il1rl1–/–and Il33–/–mice were significantly more susceptible to WNV-E218A infection, displaying reduced survival and enhanced weight loss." (PMID 37983247, 2023). "In a neonatal mouse model of influenza, infection-induced IL-17A was associated with increased IL-33 production by lung epithelial cells, subsequently generating a local type 2 immune response." (PMID 37783278, 2023). "IL-1 has been associated with the host response during UPEC mediated infection, but IL-18 and IL-33 currently lack a known role in the host response during UPEC infection." (PMID 35132157, 2022). "Here, we found that IL-33 contributes to biliary injuries and repair caused by infection with C. sinensis via type 2 cytokines." (PMID 36271450, 2022). "Our study reveals that infection-induced IL-33 production causes T cell aging by inducing thymic involution and consequently impairs host control of severe infection." (PMID 36371464, 2022). "In this study, we found that the infection of mice with C. sinensis was associated with an increase in hepatobiliary damage and liver function, while the deletion of IL-33 gene in mice was associated with a decrease in biliary fibrosis in infected mice." (PMID 36271450, 2022). "In line with the phenotype seen in ST2fl/fl/FIC mice, both Treg-sufficient and Treg-depleted CR-infected mice treated with IL-33 showed similar high susceptibility to CR infection." (PMID 33654214, 2021).
infection (continued). "The morphology of S. mansoni worms and the number of eggs in intestinal tissues were studied at different time points post-infection in S. mansoni-infected IL-33-deficient (IL-33−/−) and wild-type (WT) mice." (PMID 33482904, 2021). "This is evident as a result of the fact that IL‐33‐deficient mice show a limited elimination of infection." (PMID 32566227, 2020). "By contrast, infection in IL-33 KO mice was associated with a significant attraction of B lymphocytes, CD4+ and CD8+ T lymphocytes, as well as NK cells on Day 60, without any clear impact on spleen weight, nor on GC area, yet ensuring parasite control." (PMID 32571430, 2020). "Our team has previously reported elevated concentrations of IL-33 in the serum of patients infected with L. infantum, and showed in a mouse model of L. donovani infection, that IL-33 was associated with poorer control of infection in the liver." (PMID 32571430, 2020). "By contrast, IL‐33−/− mice are more susceptible to infection than wild‐type mice, showing impaired microbial clearance and severe tissue immunopathology." (PMID 32566227, 2020). "In certain cases, viral virulence is linked to enhanced IL-33 release, as observed upon infection with respiratory syncytial virus (RSV) in both human and mice." (PMID 30949175, 2019). "Our IL-33 treatment regimen caused a fivefold increase in IL-33 protein levels within the colon prior to infection." (PMID 31221971, 2019). "In accordance with the myeloid cell data, the increase in the type-2-associated cytokine, IL-4, occurred only after infection as uninfected IL-33-treated mice had equivalent levels of IL-4 relative to controls." (PMID 31221971, 2019). "Interesting, the expression of TSLP mRNA was more highly evident and associated with bronchial epithelial cell area in male mice at 4-weeks post-infection, whereas IL-33 appeared to be more contained and associated with alveolar areas as assessed by RNAscope." (PMID 31076663, 2019). "In HIV infection, gut damage occurs early after infection, which can cause the elevation of IL-33 and sST2." (PMID 30564243, 2018). "The analysis showed that allergic reactivity was inversely associated with the presence of infection and positively associated with low (≤100 pg/ml) serum concentration of IL-10 and high (>100 pg/ml) concentration of IL-33." (PMID 30713536, 2018). "The genes encoding the regulatory cytokines IL-10 and IL-33 were also expressed principally in MΦs before infection and upregulated after infection." (PMID 29408905, 2018). "Upon tissue injury, IL-33 likely functions as a double-edged sword; on one hand IL-33 is critical for tissue repair or elimination of infection while on the other, excessive production can cause tissue and organ damage." (PMID 28387719, 2017). "Interleukin-33 (IL-33), which is a member of the interleukin-1 (IL-1) cytokine family, is produced in response to the cell damage caused by infections or by breaches in tissue barrier integrity." (PMID 28553430, 2017). "Enhanced resistance to infection after allergen challenge was associated withincreased gene expression of alternatively activated macrophages (M2 macrophages) and IL-33 levels." (PMID 28128217, 2017). "Here, we demonstrated the effect of endogenous IL-33 during L2-MHV3 infection in mice by using IL-33-deficient mice (IL-33 KO)." (PMID 28607531, 2017). "The IL-33-mediated host responses and its role in infection-associated renal injury appear to be organism- and model-dependent." (PMID 28387719, 2017). "In murine models, sialylated IgGs bind to DC-SIGN, inducing the production of IL-33, an infection-linked cytokine that activates basophils to produce IL-4, leading to the upregulation of the inhibitory Fc receptor FcγRIIb." (PMID 29098000, 2017). "The L2-MHV3 infection significantly induced weight loss of both WT and IL-33 KO mice at 48 h and 72 h PI but with a greater loss as soon as 48 h PI in IL-33 KO mice." (PMID 28607531, 2017).
infection (continued). "In our model, we observed higher levels of both mediators: IFN-γ and NO, following infection of IL-33 signaling-deficient mouse (ST2−/−) with ROCV." (PMID 27334012, 2016). "Previous reports demonstrate that CNS IL-33 signaling is related to protection following experimental infection with Toxoplasma gondii, and the authors found that IL-33 deficiency leads to increased parasite burden and pathology in the brains of infected mice." (PMID 27334012, 2016). "To further investigate how IL-33 regulates immune responses and why IL-33-/- mice have attenuated weight loss and kidney injury, we examined a panel of immune cytokines in the kidney after infection." (PMID 26943125, 2016). "Based on our in vitro studies in human ECs and in vivo studies in WT and IL-33-/- mice, we have proposed a pathogenic role of IL-33 in endothelial dysregulation during the infection." (PMID 26943125, 2016). "In this same study, IL-33 deficiency led to greater hemorrhaging at day 3 post infection, along with reduced eosinophil recruitment to the lung." (PMID 25028340, 2014). "Mice resistant to T. muris infection produce more IL-33 at day 3 post infection compared to susceptible animals." (PMID 23053395, 2012). "IL-33-mediated resistance seems to be T cell-dependent because IL-33-treated SCID mice remain susceptible to infection despite developing gut pathology." (PMID 23053395, 2012). "We previously compared two strains, Karp and UT176 (distinct from UT76 used in the current study) and found that Karp caused greater disease severity in a mouse model of infection, and induced more proinflammatory cytokines including IL33 in a dual RNAseq analysis of Ot-infected HUVEC cells." (PMID 40587585, 2025). "The reduction in inflammation associated with AAV‐IL33 infection may be confounded by IL33's direct effects." (PMID 40605604, 2025). "The antibiotic-induced deficiency in IL-33 in acute CDI could therefore predispose to recurrent infection by impairing the production of antitoxin B antibody." (PMID 40048372, 2025). "Also, our mouse data suggest that increased endogenous IL-33 is more likely a physiologic response to high-risk infection, given the protective role of exogenous IL-33 in stimulating protective humoral immunity." (PMID 40048372, 2025). "IL-33 was upregulated in patients at the highest risk for rCDI, suggesting that IL-33 could predispose to recurrent infection." (PMID 40048372, 2025). "Previous reports indicate that tissue injury, whether sterile or infection-derived, is associated with increased IL-33 release following cell destruction, which contributes to Tregs accumulation." (PMID 39883714, 2025). "In addition, IL-33, a chromatin-associated nuclear cytokine from the IL-1 superfamily, is released upon cellular damage and exerts potent actions upon infection." (PMID 40565198, 2025). "In a model of severe bronchiolitis using IRF7-deficienct mice, neonatal infection with PVM led to release of IL-33 and HMGB1 (high-mobility group box 1), another nuclear alarmin, both of which contributed to ILC2 proliferation, type 2 inflammation, and airway remodeling." (PMID 35493465, 2022). "Downregulation of IL-33 signaling by adding soluble ST2 made mice more susceptible to infection." (PMID 34400793, 2022). "Treatment with IL-33 significantly protected mice from infection and weight loss." (PMID 34400793, 2022). "Increased IL-33 levels in severe infections may result from an inflammatory storm caused by strong interactions between activated immune cells." (PMID 36362440, 2022). "Furthermore, IL-33−/− mice showed higher susceptibility to infection and severe gut tissue destruction in a model of Salmonellosis9." (PMID 33654214, 2021). "This may be due to the fact that increased IL-33 might exacerbate organ injuries caused by inflammation after infection." (PMID 33178181, 2020).